IL33 (interleukin 33)
Diseases named in the same sentence as IL33 in open-access papers (continued):
Sharing a sentence is not in itself a finding about the gene and the disease.
Chronic colitis (6 papers, 2017 to 2021). A chronic inflammatory disease of the large intestine (colon, cecum and rectum). "Surprisingly, we found that neither Il33 expression, nor IL-33 producing fibroblasts were increased during the development of chronic colitis in Il10-deficient mice, although Il33 expression could be induced in Il10−/− mice by epithelial injury with DSS." (PMID 33953267, 2021). "The role for endogenous IL-33 in chronic colitis as well as regulation of IL-33 expression remains uncertain." (PMID 33953267, 2021). "To determine the role of endogenous IL-33 in chronic colitis, we bred Il10−/−/Il33−/− mice and compared them to littermate Il10−/−/Il33+/+ mice." (PMID 33953267, 2021). "When it comes to chronic colitis, some researchers believed that IL-33 alleviates the syndrome by suppressing Th17 and Th1 responses." (PMID 32676507, 2020). "The percentages and absolute numbers of CD25-expressing T cells (CD4+CD25+) and CD25-expressing B cells (B220+CD25+) in T-LPLs were drastically higher in the MLN of the IL-33-treated chronic colitis group than that of the control group." (PMID 30539029, 2018). "The level of IL-13 was noticeably increased with anti-CD3 and anti-CD28 mAb stimulation, and similar results were observed without any stimulation in the supernatants of the MLN of the IL-33-treated chronic colitis group compared with the control group." (PMID 30539029, 2018). "Our data provide clear evidence that IL-33 plays a protective role in DSS-induced chronic colitis, which is closely related to increasing Breg and Treg responses in the MLN of mice as well as suppressing Th17 cell responses." (PMID 30539029, 2018). "Measurement of cytokine concentrations in the culture supernatants of the MLN without any stimulation manifested that the levels of IL-6, IL-1β, and IL-23 were sharply decreased in the IL-33-treated chronic colitis group compared with the control group." (PMID 30539029, 2018). "The level of IL-17A with anti-CD3 and anti-CD28 mAb stimulation was noticeably reduced in the IL-33-treated chronic colitis group compared with the control group, while a similar concentration of IL-17A without any stimulation was observed in these two groups." (PMID 30539029, 2018). "We formerly showed that IL-33 alleviated DSS-induced chronic colitis by suppressing Th17 cell response in colon lamina propria." (PMID 30539029, 2018). "The percentage and the absolute numbers of macrophage (CD11b+Gr-1−F4/80+) in the MLN were dramatically higher in the IL-33-treated chronic colitis group than in the control group." (PMID 30539029, 2018). "In conclusion, our data here shows that IL-33 treatment substantially ameliorates the development of DSS-induced chronic colitis by decreasing Th17 cell response and increasing both regulatory B cell and regulatory T cell responses." (PMID 30539029, 2018). "In accordance with above observation, our data demonstrated that the expression level of IL-10, the absolute number and percentage of CD4+CD25+ and CD4+IL-10+ Tregs in MLN of mice with DSS-induced chronic colitis, were strikingly higher in the IL-33 group than in PBS group." (PMID 30539029, 2018). "IL-33 was administered by intraperitoneal injection to mice with DSS-induced chronic colitis." (PMID 30539029, 2018). "Furthermore, we detected IFN-γ or IL-17A-producing CD4+ T cells in the MLN of IL-33-treated and untreated chronic colitis mice." (PMID 30539029, 2018). "Moreover, IL-33 treatment also decreases Th17 cell response in the MLN of mice with DSS-induced chronic colitis." (PMID 30539029, 2018). "And we speculate that IL-33 would promote the Treg or Breg responses leading to the attenuation of DSS-induced chronic colitis." (PMID 30539029, 2018). "The higher level of Breg responses may be one of the reasons why IL-33 can suppress the DSS-induced chronic colitis." (PMID 30539029, 2018). "In conclusion, deficiency of IL-33 does not alter the severity of chronic colitis in Il10−/− mice." (PMID 33953267, 2021).
Chronic colitis (continued). "Moreover, we speculated that IL-33 would promote the Treg or Breg responses leading to the attenuation of DSS-induced chronic colitis." (PMID 30539029, 2018). "Other study also noted that administration of IL-33 suppressed the Th17 response secreted by lamina propria lymphocytes (LPL) and replaced the Th1 response with Th2 in chronic colitis induced by sodium dextran sulfate (DSS) in mice." (PMID 34324507, 2021). "We show that IL-33 treatment increases both Breg and Treg responses in the MLN of mice with DSS-induced chronic colitis." (PMID 30539029, 2018). "So, we investigated the role of IL-33 on Bregs and Tregs in the MLN of DSS-induced chronic colitis mice." (PMID 30539029, 2018). "Next, we investigated the effect of IL-33 on both Treg and Breg responses in the MLN of mice with DSS-induced chronic colitis." (PMID 30539029, 2018). "Consistent with this, in this study, we found that IL-33 induces Bregs (CD19+CD25+) and IL-10-producing Bregs (CD19+IL-10+) in the MLN of mice with DSS-induced chronic colitis." (PMID 30539029, 2018). "Interestingly, IL-33 may be involved in the pathogenesis of DSS-induced acute colitis by promoting Th2 cell response in intestinal mucosa of mice, while IL-33 alleviates DSS-induced chronic colitis in C57BL/6 mice colon lamina propria by suppressing Th17 cell response as well as Th1 cell response." (PMID 28423665, 2017). "Collectively this data does not support a role for IL-33 in regulating spontaneous chronic colitis in Il10−/− mice." (PMID 33953267, 2021). "Accordingly, using double knockout mice, we demonstrated that IL-33 does not play a significant role in the development or progression of chronic colitis in Il10−/− mice." (PMID 33953267, 2021). "The level of IL-4 and IL-5 with anti-CD3 and anti-CD28 mAb stimulation and without any stimulation was markedly increased in the IL-33-treated chronic colitis group compared with the control group." (PMID 30539029, 2018). "The level of IFN-γ with anti-CD3 and anti-CD28 mAb stimulation and without any stimulation was strikingly reduced in the IL-33-treated chronic colitis group compared with the control group." (PMID 30539029, 2018). "The level of IL-10 with anti-CD3 and anti-CD28 mAb stimulation and without any stimulation was significantly increased in the IL-33-treated chronic colitis group compared with the control group." (PMID 30539029, 2018). "Moreover, compared to the chronic colitis mice treated with PBS, those mice treated with IL-33 showed an enormous reduction in the expression of ROR-γt mRNAs." (PMID 30539029, 2018). "Moreover, compared to the chronic colitis mice treated with PBS, those mice treated with IL-33 showed a marked increase in the expression of Foxp3 mRNAs." (PMID 30539029, 2018). "Il33 was not increased in Il10−/− mice with chronic colitis compared to WT mice." (PMID 33953267, 2021). "Despite these advances, it is not yet known whether IL-33 played a role in the MLN during the development of DSS-induced chronic colitis." (PMID 30539029, 2018).
chronic gastritis (6 papers, 2015 to 2024). Inflammation of the stomach that is chronic in nature. "For example, IL-33 contributes to host defense against parasitic and bacterial infections and exerts cardioprotective effects, however, in chronic gastritis, IL-33 release after parietal cell loss induces IL-13 production from ILC2s to promote intestinal goblet cell differentiation in mice." (PMID 39193325, 2024). "Specifically, the process is mediated by the activity of cytokines, such as IL-33 and IL-13, and cell types, such as mast cells, M2 macrophages, and eosinophils, which promote diffuse and chronic gastritis-dependent metaplasia." (PMID 38730659, 2024). "In particular, the activity of cytokines, such as IL-33 and IL-13, and cell types, such as mast cells, M2 macrophages and eosinophils, are intertwined in the process, promoting chronic gastritis-dependent and more diffuse metaplasia." (PMID 38339273, 2024). "IL-33 may play a crucial role in the inflammatory response and induction of the chronic gastritis and severity of inflammatory changes in the gastric mucosa." (PMID 27014647, 2015). "Nonetheless, it has been reported that IL-33 induces IL-13 production from ILC2s to promote intestinal goblet cell differentiation within the colons of mice, indicating that the IL-33/IL-13 axis might play a relevant role in inducing intestinal metaplasia in the context of chronic gastritis." (PMID 38339273, 2024).
Dry skin (6 papers, 2018 to 2025). Skin characterized by the lack of natural or normal moisture. "Recent research has shown that IL-33 also acts directly on sensory neurons to mediate pruritus associated with dry skin, as demonstrated in human plasma studies and mouse models." (PMID 41155460, 2025). "The inflammation associated with this dry skin pathogenesis arises from IL-33 production in keratinocytes, and it is accompanied by leukocyte infiltration and elevated IL-13 production from dermal ILC2s." (PMID 38319737, 2024). "Our results reveal that S. aureus infection–elicited keratinocyte necroptosis contributes to IL-33–mediated type 2 inflammation, which exacerbates the pathogenesis of dry skin." (PMID 38319737, 2024). "IL-33 and ST2 levels are elevated in epidermis of AD patients and high-level IL-33 in serum significantly correlates with excoriation and xerosis scores." (PMID 29987222, 2018).
esophageal adenocarcinoma (6 papers, 2015 to 2025). A malignant tumor with glandular differentiation arising predominantly from Barrett mucosa in the lower third of the esophagus. "Recent studies have shown that IL‐33/ST2 can regulate the progression of esophagitis to esophageal adenocarcinoma." (PMID 40860436, 2025). "In the esophageal adenocarcinoma rat model, the mRNA expression of IL-33 was significantly higher in the 10w and 16w groups than that in other groups, and increased with the upgrade of pathological stage." (PMID 36110250, 2022). "We further examined the effect of IL-33 on tumor-related cytokines and found that the mRNA expressions of IL-4 and IL-6 were significantly higher in the esophageal adenocarcinoma cells after IL-33 stimulation." (PMID 36110250, 2022). "IL-33 promotes the secretion of the tumor-promoting cytokine IL-6 by esophageal adenocarcinoma cells." (PMID 36110250, 2022). "In the next study, we will also explore the role of IL-33 in the tumor microenvironment of esophageal adenocarcinoma." (PMID 36110250, 2022). "Similarly, IL-33 promoted IL-6 secretion via ST2L in esophageal adenocarcinoma cells (OE19 and OE33)." (PMID 37834290, 2023). "IHC showed that IL-33 was mainly expressed in the cytoplasm in esophageal adenocarcinoma cells." (PMID 36110250, 2022). "Nonetheless, the biological function of IL-33 in human esophageal adenocarcinoma remains unknown." (PMID 36110250, 2022). "IL-33 not only promoted the proliferation, migration, invasion and EMT of esophageal adenocarcinoma cells through ST2, but also promoted the secretion of IL-6." (PMID 36110250, 2022). "Since IL-33 has been proven to facilitate inflammation in GERD, we investigated the function of IL-33/ST2 signaling in the development of esophageal adenocarcinoma." (PMID 36110250, 2022). "IL-33 is a cytokine involved in the formation of EAC and has been shown to increase the proliferation, migration, and invasion of esophageal adenocarcinoma cells in in vitro through ST2." (PMID 36110250, 2022). "Our research also found IL-33 promoted the proliferation, migration, invasion and EMT of esophageal adenocarcinoma cells through ST2." (PMID 36110250, 2022). "Two esophageal adenocarcinoma cell lines (OE33: poorly differentiated adenocarcinoma; OE19: moderately differentiated adenocarcinoma) and human normal esophageal cells (HEECs) were used to detect IL-33." (PMID 36110250, 2022).
fungal infections (6 papers, 2019 to 2025). "Cytokines involved in granuloma development, primarily IL-33, IL-5, and IL-13 were evaluated considering previous data on fungal infections." (PMID 34829225, 2021). "While the broad and potent consequences of IL-1α/β and IL-33 signaling are known, the induction of these cytokines during fungal infection is less clear." (PMID 33643264, 2021). "The finding that IL-33R/ST2 signaling suppresses IL-22 is novel, but a recent study revealed IL-33 regulates IL-17A and IL-22 in fungal infection." (PMID 31057534, 2019). "The role of IL-33 signaling is now being explored in the context of fungal infection." (PMID 33643264, 2021). "IL-33 enhances macrophage cytokines secretion and CXCR2 expression in fungal infections to drive neutrophil recruitment and bactericidal capacity." (PMID 37153553, 2023).
Gastric Metaplasia (6 papers, 2015 to 2024). Intestinal metaplasia of the gastric mucosa is an intermediate precancerous gastric lesion in the gastric cancer cascade from chronic gastritis and atrophy to dysplasia and adenocarcinoma. "After chronic IL33 treatment, WT mice develop gastric metaplasia and hypoplasia with characteristic loss of surface mucins and glandular mucous metaplasia." (PMID 28210674, 2015). "Moreover, IL33 responsive ILC2s have been linked to Helicobacter pylori driven gastric metaplasia in humans and mice." (PMID 37898600, 2023). "However, STAT3 was highly activated, leading to Th2-mediated gastric metaplasia, suggesting that IL33 may be capable of driving gastric disease under specific circumstances." (PMID 28210674, 2015). "IL33 is mainly induced by chronic phosphorylation of signal transducer and activator of transcription 3 (STAT3), and previous studies have shown that overactivated STAT3 is involved in gastric inflammation and can lead to Th2-mediated gastric metaplasia." (PMID 36275647, 2022).
Hyperglycemia (6 papers, 2016 to 2022). An increased concentration of glucose in the blood. "In our study, hyperglycemia was associated with lipid peroxides formation and secretion of proinflammatory cytokines, particularly IL-6, IL-31 and IL-33." (PMID 32824505, 2020). "In our study, hyperglycemia was associated with high levels of IL-33 in cell lysates, the effects being attenuated by quercetin, both doses of PhyH and low doses of PhyF." (PMID 32824505, 2020). "Our results clarify the role of high glucose in the inhibition of IL-17-induced IL-33 expression via glucose glycation in keratinocytes and reveal that hyperglycaemia is a possible causative mechanism of decreased REG3A by IL-33 in diabetic skin wounds." (PMID 27830702, 2016). "Our results suggest associations between the host immune response and hyperglycemia in critically ill septic patients particularly implicating the interleukin-1 axis (IL-1ra), the interleukin-33 axis (ST2), and the host response to bacterial infections (procalcitonin, pentraxin-3)." (PMID 33755703, 2021). "In conclusion, Hyperglycemia in diabetic mice inhibited the expression of IL-33 in the dermal wound." (PMID 36550940, 2022). "It was also found that hyperglycemia inhibits the expression of IL-33 in mouse myocardium, thereby aggravating ischemia/reperfusion-induced myocardial injury in diabetic mice." (PMID 36550940, 2022). "Hyperglycemia in the damaged skin tissue of diabetic mice can inhibit the expression of IL-33, which is one of the reasons why skin wounds in diabetic patients are difficult to heal." (PMID 36550940, 2022). "It has been reported that hyperglycemia suppresses the expression of IL-33 in a diabetic mouse wound excision model and decreases the expression of REG3A in keratinocytes, thereby increasing inflammation in skin wounds." (PMID 36550940, 2022). "In hyperglycemia, the inhibitory effect on IL-33 secretion was noticed after a low dose of PhyF extract and after both doses of PhyH." (PMID 32824505, 2020). "Particularly PhyF extract, diminished lipid peroxidation and inhibited the IL-31 and IL-33 secretions induced by hyperglycemia." (PMID 32824505, 2020). "IL-33 secretion increased in cells exposed to hyperglycemia medium compared to cells in normoglycemia (p < 0.001)." (PMID 32824505, 2020). "If given 6 and 12 days after the disease induction IL-33 can still significantly attenuate development of hyperglycemia." (PMID 30498495, 2018). "In the groups of mice that received IL-33 from day 6, two out of 7 animals and from day 12 three out of 7 developed hyperglycemia presenting the partial effect of IL-33 if given after the onset of disease." (PMID 30498495, 2018). "IL-33 given simultaneously with the application of STZ completely prevented the development of hyperglycemia, glycosuria and profoundly attenuated mononuclear cell infiltration." (PMID 30498495, 2018). "In diabetic mouse skin, hyperglycaemia inhibits the expression of IL-17-induced IL-33 via glucose glycation." (PMID 27830702, 2016). "Collectively, these data demonstrate that hyperglycaemia inhibits IL-17 to induce IL-33 expression, thus leading to defective REG3A expression in the skin wounds of diabetic patients." (PMID 27830702, 2016). "The highly dependence of IL-33 functionality on cellular medium and also on normal or pathologic conditions may explain its different behavior in normo- and hyperglycemia." (PMID 32824505, 2020). "In our study, the NFkB/pNFkB ratio increased in hyperglycemia compared to normoglycemia, suggesting the activation of the NFkB transcription factor in hyperglycemic conditions, in correlation with the increase of oxidative stress and inflammatory markers, especially IL-6, IL-31 and IL-33." (PMID 32824505, 2020). "Our study also showed that the administration of IL-33 after the onset of hyperglycemia has a therapeutic effect in TG mice which was not seen in WT mice." (PMID 34803672, 2021).
IgG4-related disease (6 papers, 2017 to 2025). "It was found that in IgG4-related disease, M2 macrophages promote the production of several fibrogenic cytokines (IL-33, IL-1β, and TGF-β) via NF-κB signaling, leading to severe fibrosis in the affected organs." (PMID 39328595, 2024). "In conclusion, IL-33 plays an important role in the development of IgG4-related diseases as an important inducer of type 2 immunity and an important pro-fibrogenic factor." (PMID 34589505, 2021). "In IgG4-related disease (IgG4-RD), CD163+ M2 Mφs promote fibroblast activation and fibrosis by releasing profibrotic cytokines (e.g., IL-33, TGF-β) through the TLR7/IRAK4/NF-κB pathway." (PMID 41164198, 2025).
intestinal infections (6 papers, 2010 to 2025). "The IL-1β secretion, which controls the innate cytokines IL-25 and IL-33 production, both critical for the Th2 promotion, has been proposed as a mechanism to assure the chronicity of the parasite in intestinal infections by nematodes." (PMID 30967874, 2019). "IL-33 has been reported to reduce colonization and pathological effects in gastrointestinal infection." (PMID 27014647, 2015). "IL33 has been shown to reduce colonization and pathologic outcomes in murine models of intestinal infection, raising the prospect that it is a gut alarmin." (PMID 28210674, 2015). "Additional evidence for a role of the IL33/IL1RL1 axis in host defense comes from an animal study showing the protective role of IL33 in intestinal infection with nematodes." (PMID 21629437, 2010). "Since IL-33 rescues RAG2-/-, but not RAG2-/- γc-/-, mice from Clostridioides difficile and amebic infection, IL-33-ILC2 exerts host protection from these intestinal infections." (PMID 35707544, 2022).